BRCA1 (BRCA1 DNA repair associated)
Diseases named in the same sentence as BRCA1 in open-access papers (continued):
Sharing a sentence is not in itself a finding about the gene and the disease.
breast cancer (continued). "In 24 cases, a negative result (i.e., no BRCA1/2 variants reported) affected the breast cancer risk assessment and screening recommendations provided for family members." (PMID 33654310, 2021). "This query revealed that the Fanconi Anemia pathway is selectively essential in BRCA1-mutated ovarian cancer models but not in BRCA1-wild type ovarian cancer, BRCA1-mutated breast cancer, or BRCA1-wildtype breast cancer models." (PMID 34663427, 2021). "To determine whether inhibition of PARP attenuates progression of BRCA1-mutant breast cancer, we examined the efficacy of AZD2281 in vivo using the same set of allograft models as used for irradiation studies." (PMID 33767581, 2021). "Their analysis revealed a prevalence rate of 2.2% among early onset breast cancer BRCA1/BRCA2 mutation negative patients, unselected for family history and 0.9% if there were no additional features indicative of LFS." (PMID 33245408, 2021). "We have recently demonstrated a significant association between total blood arsenic levels and the risk of breast cancer in a population of Polish women who did not carry a BRCA1 mutation." (PMID 34283078, 2021). "About 78.2% of the BRCA1-deficient mammary tumors do not express ERα or PR, though about 60% of the tumors showed detectable level of ERBB2." (PMID 34815798, 2021). "To determine whether combining irradiation and PARP inhibition more effectively suppressed BRCA1-mutant breast cancer, we tested the efficacy of this combination in a preclinical allograft model." (PMID 33767581, 2021). "Tumor suppressor genes, such as BRCA1, could be inhibited in tumors by promoter hypermethylation, which may be an important mechanism of primary breast cancer progression." (PMID 34778045, 2021). "In addition to their efficacy for treating breast cancer, we have previously reported that PARP inhibitors are also effective for preventing the development of mammary gland tumors in BRCA1-deficient mice." (PMID 33441637, 2021). "Preclinical studies suggest that BRCA2-mutated but not BRCA1-mutated breast cancers are responsive to treatment with checkpoint inhibitor monotherapy." (PMID 34067105, 2021). "Furthermore, CtIP depletion drastically reduced the viability of a panel of BRCA1 mutant breast cancer cell lines, implying a synthetic sick genetic interaction between these two factors." (PMID 33608267, 2021). "Primary prevention of breast cancer is not yet a reality except by undergoing prophylactic mastectomy for those who have the BRCA1 or BRCA2 gene mutation, known to cause breast cancer." (PMID 34437623, 2021). "Furthermore, we have assessed disease outcomes in BRCA carriers, and we have observed a relatively high proportion of contralateral breast cancer and ovarian cancer occurrence that were more frequently observed in BRCA1 carriers." (PMID 34490083, 2021). "The extension and follow-up data from 2011 even reported a decrease in breast cancer risk associated with HRT in BRCA1 mutation carriers with and without RRBSO." (PMID 33885953, 2021). "As a gene directly related to hereditary breast cancer, the possibility of a regulatory relationship between Brca1 and lncRNA is high and may be a potential biomarker for breast cancer and a therapeutic target." (PMID 34956935, 2021). "Newer effective personalized therapies, including poly-ADP-ribose polymerase (PARP) inhibitors targeting BRCA1 or BRCA2 pathogenic mutations directly or via their pathways are increasingly available for ovarian and breast cancer patients who are carriers of such variants." (PMID 34072979, 2021).
breast cancer (continued). "Breast cancer is linked to several distinct life events, such as genetic mutations to the BRCA1 (breast cancer gene 1) and BRCA2 (breast cancer gene 2) genes, high breast density, family history of the disease, late full-term pregnancy, lack of physical activity, and smoking and alcohol consumption." (PMID 34638847, 2021). "An association between BRCA1 and EMT has been established in breast cancer." (PMID 34001250, 2021). "In this paper, we found that BRCA1 and GATA3 expressions are positively correlated and that BRCA1 mutation is associated with the enhanced methylation of the GATA3 promoter and reduced expression of the GATA3 gene in human breast cancers." (PMID 34373738, 2021). "As expected, the BRCA1-mutant breast cancer organoid was sensitive to olaparib." (PMID 34140467, 2021). "Additionally, it was shown that UBE2T played a critical role in the development and/or progression of breast cancer through the interaction with and the regulation of the BRCA1/BARD1 complex." (PMID 34787051, 2021). "The incidence of breast cancer in BRCA1 mutation carriers is 2.4% and 1.7% in North America and Poland, respectively; these occurrences are significantly higher than the incidence of breast cancer in individuals without the BRCA1 mutation." (PMID 34779589, 2021). "Among the individuals with pathogenic variants, 50% were diagnosed with breast cancer and had mutations in BRCA1, CDH1 and MUTYH – gene not typically associated with this cancer." (PMID 33827469, 2021). "In future studies, it will be necessary to identify the specific regulatory mechanisms of lncRNAs for these two target genes (Brca1 and Dennd5d), especially Brca1, which might identify potential biomarkers and therapeutic targets for breast cancer." (PMID 34956935, 2021). "BRCA1 positive breast cancer subgroup also has high rate of pCR – up to 61 %." (PMID 34233740, 2021). "Notably, all the cancer cells from the four models showed high Krt18 expression, and only some cells from the BRCA1 model, a basal-like breast cancer model, showed a detectable Krt5 transcript." (PMID 34497807, 2021). "In most of the examined patients with breast cancer (89.25%), we did not identify pathogenic BRCA1/2 variants." (PMID 33918338, 2021). "Locus-specific loss of heterozygosity (LOH) (i.e. absence of wild-type BRCA1 copy) is observed in BRCA1 breast cancers; however, the impact of LOH on BRCA1 variants are still under investigation." (PMID 34855882, 2021). "Importantly, these results confirm the role of Brca1 in suppressing EMT in a mammary tumor cell autonomous manner." (PMID 33478572, 2021). "We sought to develop OlaR TNBC cells since olaparib has shown promising anti-tumor activity in Her2/neu-negative metastatic breast cancer patients with BRCA1 mutations and is FDA approved for TNBC treatment." (PMID 34367977, 2021). "Also in adult patients, tumor mutations, such as in EGFR, BRCA1/BRCA2, and SMAD4 genes, decrease engraftment rates in adenocarcinoma, breast cancer, and pancreatic cancer, respectively." (PMID 33837665, 2021). "Interaction of BAP1 with BRCA1 has been shown to inhibit breast cancer growth." (PMID 33916178, 2021). "The sensitivity of tumors with BRCA1/2 disruption demonstrated in clinical use of PARPis suggests similar success could be achieved with such a strategy for ovarian and breast cancers." (PMID 34070674, 2021).
breast cancer (continued). "According to limited data from available studies, HRT following RRBSO in BRCA1/2 mutation carriers does not seem to have an adverse effect or negate the reduction in breast cancer risk associated with RRBSO." (PMID 33885953, 2021). "Most relevant from a clinical point of view, we observed SP18–28-mediated killing of BRCA1-mutated breast cancer cells, whereas no apparent toxicity was detected in nontumorigenic cell lines." (PMID 33608267, 2021). "Thus, different ovarian cancer cluster regions (OCCRs) and breast cancer cluster region (BCCRs) can be formulated for both the BRCA1 and BRCA2 genes." (PMID 34680878, 2021). "As a consequence, breast cancer is becoming increasingly heterogeneous as it is further divided into categories of ‘basal-like’ and ‘luminal’ cancers, and according to known single gene markers such as BRCA1/2 (ibid)." (PMID 33940433, 2021). "Therefore, physicians can evaluate VUS variant with given risk score 87 patients with pathogenic, 23 with likely pathogenic, 128 VUS, 29 likely benign and 1 benign BRCA1 and BRCA2 gene variants together with 14 other clinical breast cancer risk factors." (PMID 34828379, 2021). "About 10%-15% of breast cancer cases are hereditary, which might be related to the mutations of BRCA1 (Breast cancer susceptibility gene 1) and BRCA2 (Breast cancer susceptibility gene 2)." (PMID 33407485, 2021). "These additional treatments could have been spared if BRCA1/2 carriers with unilateral breast cancer underwent RRM at the time of initial surgery." (PMID 34285295, 2021). "There are guidelines for management of genetically caused breast cancer with mutations other than BRCA1 and 2, but these are not as rigid as the guidelines for women with BRCA mutation." (PMID 33996049, 2021). "Indeed, nearly half the deaths (44%) in BRCA1/2 PV carriers with breast cancers were due to other cancers (6/16) or old age (1/16)." (PMID 34312777, 2021). "In order to evaluate whether BRCA1 may regulate autophagy induction in breast cancer cells, BRCA1-KO MCF-7 cells were also used." (PMID 33473172, 2021). "In this study, AhR and amphiregulin were shown to regulate the production of chemokines (e.g., granulocyte colony-stimulating factor, CXCL1, CXCL2, and C-C motif chemokine ligand 5) to attract monocytes into the TME in a BRCA1-deleted mouse mammary tumor model." (PMID 33498875, 2021). "Among all patients with breast cancer without selection bias, the BRCA1/2 mutation retention rate was 4.2–6.1% (BRCA1: 1.45–3.7%, BRCA2: 2.4–3.5%)." (PMID 32862296, 2021). "In our previous study on subjects without germline mutations in BRCA1, we reported that increased blood arsenic levels are significantly associated with high breast-cancer risk." (PMID 34283078, 2021). "Interestingly, we showed that PRMT1 also can enhance breast cancer cell proliferation after inhibiting BRCA1 or c-Myc functions by their specific inhibitor." (PMID 34775498, 2021). "In this descriptive study we have established the prevalence of BRCA1 germline mutations in a group of 20 pregnancy associated breast cancer patients, which were selected regardless of family history." (PMID 34011307, 2021). "In this study, contralateral RRM demonstrated no survival benefit for BRCA1/2 mutation carriers with breast cancer." (PMID 34285295, 2021). "In some studies, the ATM mutation (causing Ataxia Telangiectasia) was reported as a risk factor for breast cancer patients who did not have a BRCA1/2 mutation." (PMID 34493284, 2021).
breast cancer (continued). "Using inherited breast cancer as an example, follow-up strategies to manage elevated breast cancer risks may include either enhanced breast cancer screening or bilateral mastectomy for high penetrance genes, such as BRCA1/2 and PALB2." (PMID 34645413, 2021). "It is notable that the frequency of male patients is also higher in the BRCA1 mRNA-high group in breast cancer, which may instead support a possible interaction between male hormones and BRCA1 that promotes the development of these cancers." (PMID 34611475, 2021). "Nonetheless, more than 60% of breast cancer patients with genetic characteristics or family aggregation do not carry BRCA1/2 mutations." (PMID 34917121, 2021). "On the contrary, in ovarian cancer, the expression of BRCA1 was the lowest in samples with somatic BRCA1 mutations compared to other groups, while the expression of BRCA2 expression showed a similar pattern as in breast cancer." (PMID 33525353, 2021). "Inherited mutations in BRCA1, BRCA2, and PALB2 cause a high risk of breast cancer." (PMID 33893322, 2021). "The medical research revealed a need to develop separate decision aids for women with BRCA1/2 mutations (A) without a history of cancer (previvors) and (B) with a history of unilateral breast cancer (survivors)." (PMID 34090422, 2021). "When comparing AMH of women carrying BRCA1-2 pathogenic variants with and without breast cancer to wild type women with and without breast cancer, five studies were included." (PMID 34627117, 2021). "Considering the importance of PI3K/Akt signaling for CSC induction and maintenance in breast cancer, its long-term activation could contribute to developing the treatment-resistant, basal-like phenotype in BRCA1-mutant tumors." (PMID 34638302, 2021). "Expression of two potential downstream effectors of SOX11 signalling we recently identified in breast cancers cells, Mex3a and Rcor2, which have links to stem cell proliferation and reprogramming, respectively, were also substantially reduced in Brca1.3 cells with reduced Sox11 levels." (PMID 33969421, 2021). "Although the clinical success of PARP inhibitors for women with germline BRCA1/2 pathogenic variants is clear, the utility of using PARP inhibition to treat breast cancers with somatic BRCA1/2 mutations is not known." (PMID 33854152, 2021). "The poly (ADP-Ribose) polymerase (PARP) inhibitor olaparib has shown antitumor activity in patients with ovarian or breast cancer with or without BRCA1/2 mutations." (PMID 33627685, 2021). "Interestingly, it has been reported that down-regulation of CD49f in CSCs isolated from mammary tumours of Brca1-mutant mouse model induces reduced cell migration, suggesting a role of CD49f in this process." (PMID 34203746, 2021). "High MD combined with BRCA1/2 mutations further increase breast cancer risk, yet BRCA1/2 mutations alone or in combination do not increase MD." (PMID 34209669, 2021). "After a breast cancer diagnosis, RRSO for breast cancer mortality reduction can be considered within two years to women who harbour a pathogenic or likely pathogenic variant in BRCA1 if younger than the recommended age range for ovarian cancer risk reduction." (PMID 34565426, 2021). "This cohort study compares survival rates after breast-conserving therapy vs mastectomy in BRCA1/2 variant carriers and noncarriers in a large series of unselected patients with breast cancer." (PMID 33890992, 2021). "All the cells used in this study possess wild-type breast cancer 1/2 (BRCA1/2)." (PMID 34681900, 2021). "In this scenario, the aim of the present meta-analysis was to analyze all available studies reporting clinical characteristics of BRCA1 gene hypermethylated breast cancer in women, and to pool the results in order to provide a unique clinical profile of this cancer setting population." (PMID 33808555, 2021). "Mutations in BRCA1 and BRCA2 are closely related to increased susceptibility to breast cancer." (PMID 34917121, 2021).
breast cancer (continued). "The present study compared the interaction of adipose-derived stromal cells (ADSCs) on wildtype and BRCA1-mutated breast cancer cell lines and found no increased protumor effects of CM of ADSCs." (PMID 34228231, 2021). "Two previous studies that examined the frequency of BRCA1/2 genetic testing in young breast cancer patients diagnosed at age ≤ 45 years found that 72.9% of their sample had genetic testing in one study, and 87% of the women reported testing 1-year post diagnosis in the second study." (PMID 31802423, 2021). "Furthermore, the confirmation that some triple-negative breast cancers (TNBC) are phenotypically similar to breast tumors with BRCA1 mutations has aroused the interest of researchers to study the effectiveness of PARP inhibitors in both BC with BRCA1/2 germline mutations and TNBC." (PMID 33767780, 2021). "Although mutations in BRCA1 and BRCA2 are two of the most widely known genetic determinants of breast and ovarian cancer, they are among many in a series of CPGs implicated in the formation of hereditary breast cancer." (PMID 34070674, 2021). "Clinically, BRCA1 variant carriers have a higher risk of developing triple-negative (TN) status in breast cancer, which is negative for ER, progesterone receptor (PgR), and HER2." (PMID 35008774, 2021). "The breast cancer 1/2 (BRCA1/2) genes are important players in the pathogenesis of ovarian cancer." (PMID 34571986, 2021). "In addition, p18−/−;Brca1+/− mammary tumors were enriched with cancer stem cells and significantly more metastatic than p18−/− tumors." (PMID 33478572, 2021). "A study of 107 BRCA1/2-negative women with early-onset breast cancer, multiple primary cancers, or a family history of breast cancer showed that knowledge increased significantly after predisclosure counseling and receipt of results, including knowledge in those who received negative results or VUS." (PMID 34748551, 2021). "Other breast cancer susceptibility genes that have equivalent information include BRCA2 (penetrance to age 70, 45% (95% CI, 31–56%), PALB2 (penetrance to age 70, 44% (95% CI, 37–52%) and BRCA1 (penetrance to age 70, 65% (95% CI, 44–78%)." (PMID 33803639, 2021). "The findings from this current study provide a molecular basis for a combinatory effect of high MD and BRCA1/2 gene mutations on breast cancer risk, through the repression of RASSF1A, a tumour suppressor gene known to be silenced by methylation in breast cancers." (PMID 34209669, 2021). "This case-control study showed approximately a 10-fold increased risk of breast cancer for BRCA1/2 pathogenic variant carriers, when compared with noncarriers in Chinese women." (PMID 34606182, 2021). "We demonstrated that knockdown of GATA3 in T47D human breast cancer cells or overexpression of WT Gata3 in Gata3 deficient mouse mammary tumor cells did not cause significant change of BRCA1 mRNA levels." (PMID 34373738, 2021). "Beyond the classical breast cancer subtypes based on transcriptomic data, some of these genomic alterations are expressed in different subgroups in an agnostic manner, such as fusions at NTRK gene or BRCA1/2 mutations, among others." (PMID 33925616, 2021). "This study assesses the role of VDR and GC SNPs on breast cancer (BC) recurrence and survival in a cohort of patients with a family history of breast cancer, without the pathogenic variant for BRCA1 and BRCA2." (PMID 33917614, 2021). "This paradigm is best exemplified in BRCA1 and BRCA2 pathogenic variant carriers where knowledge of the function of these genes led to the development of poly (ADP-ribose) polymerase (PARP) inhibition as a novel therapy for the treatment of breast cancers." (PMID 34439109, 2021).